TPSB2 (tryptase beta 2)
Description:
Tryptase is the major neutral protease present in mast cells and is secreted upon the coupled activation-degranulation response of this cell type. May play a role in innate immunity.
Synonyms: TPS2; tryptaseB; tryptaseC
Tractability: Small molecule: a structure with a bound ligand is known; a high-quality ligand is known; it has a binding pocket of medium quality. Antibody: UniProt places it where antibodies can reach, with medium confidence; UniProt predicts a signal peptide or a membrane-spanning region; its Gene Ontology location is reachable by antibodies, with medium confidence. PROTAC: a small molecule that binds it is known.
Target class: Enzyme; Hydrolase
Gene: Protein-coding gene on chromosome 16 (1,227,272 to 1,233,725, reverse strand). Ensembl gene ENSG00000197253.
Subcellular location: Secreted
Gene Ontology:
Molecular function: protein binding; serine-type endopeptidase activity; serine-type peptidase activity; peptidase activity
Biological process: proteolysis
Cellular component: extracellular matrix; extracellular region
Genetic constraint (gnomAD): Loss-of-function variants: 9 observed, 7.99 expected, observed/expected ratio (o/e) 1.13, 90% interval 0.67 to 1.8. That is too few expected variants to judge how well the gene tolerates losing a copy. Missense variants: 123 observed, 104.34 expected, observed/expected ratio (o/e) 1.18, 90% interval 1.02 to 1.37. Synonymous variants: 45 observed, 41.73 expected, observed/expected ratio (o/e) 1.08, 90% interval 0.85 to 1.38.
Homologues: Orthologues: chimpanzee TPSB2 (95% identical), mouse Tpsb2 (76% identical), rat Tpsb2 (75% identical), mouse Tpsab1 (74% identical), rat Tpsab1 (74% identical), zebrafish zgc:165423 (40% identical), zebrafish prss60.1 (40% identical), zebrafish prss60.2 (39% identical), Drosophila melanogaster flz (39% identical), zebrafish si:dkey-16l2.17 (39% identical), zebrafish prss60.3 (38% identical), zebrafish zgc:123295 (36% identical), and 49 more. Paralogues in human: TPSAB1 (99% identical), TPSD1 (72% identical), TPSG1 (43% identical).
Diseases named in the same sentence as TPSB2 in open-access papers:
TPSB2 is named in the same sentence as 25 diseases in open-access papers, as found by Europe PMC text mining. Sharing a sentence is not in itself a finding about the gene and the disease. The quoted sentences say what the papers report.
asthma (3 papers, 2017 to 2023). "Differential expression of CPA3 and TPSB2 between central and peripheral airways in severe asthma was confirmed by RT-qPCR." (PMID 28045928, 2017). "Direct comparison between the airways within severe asthma identified greater expression of mast cells proteases (CPA3, TPSB2, TPSAB1) in the peripheral airways." (PMID 28045928, 2017). "We found that their expression levels (except TPSB2, which had not been studied in dataset GSE67472) were also significantly upregulated in Th2-high asthma patients compared to controls in dataset GSE67472." (PMID 35550122, 2022).
COVID-19 (3 papers, 2021 to 2023). A disease caused by infection with severe acute respiratory syndrome coronavirus 2. "qPCR data showed that Control testes presented minimal expression of chymase (CMA1) and tryptase (TPSB2), whereas all testicular samples from the COVID-19 patients exhibited increased expression." (PMID 36797789, 2023). "Consistent with the serum findings from SARS-CoV-2 patients, the MC protease genes TPSB2 and TPSAB1 which encode for α- and β-tryptase, respectively, were significantly elevated in lungs from COVID-19 patients, suggesting increased activation of lung MCs in COVID-19 inflammation." (PMID 33777047, 2021). "The levels of the proteases in four patients subsequently deceased from COVID-19 were comparable to the levels in the patients with severe COVID-19: CPA3 (21.54 ±6.6 vs. 22.25 ±5.7 ng/ml, p = 0.72); CMA1 (2426 ±1113 vs. 2387 ±720 ng/ml, p = 0.73) and for TPSB2 (27.5 ±17 vs. 30.04 ±17 ng/ml, p=0.95)." (PMID 36225927, 2022).
allergic reactions (2 papers, 2023 to 2025). "The TPSB2 gene encodes a serine protease that is the most abundant mediator stored in mast cell granules and plays a central role in activating innate immunity, inflammatory and allergic reactions." (PMID 40264151, 2025).
breast carcinoma (2 papers, 2023 to 2025). "Several previous studies showed that TPSB2 was abnormally expressed or somatic genomic alterations occurred in some cancers including breast cancer and gastric cancer." (PMID 37938151, 2023).
airway hyperresponsiveness (1 paper, 2023). "Of those dysregulated genes, four were associated with immune-mediated inflammatory diseases (Csf2; Crlf2; Rnase2b; Tpsb2) and one with airway hyperresponsiveness (Prg2), while Il-13 was associated with both of those pathways." (PMID 36834405, 2023).
depression (1 paper, 2026). "Consistently, the mRNA levels of mast cell‐specific proteases, such as Chymase 1 (CMA1), Carboxypeptidase A 3 (CPA3), and Tryptase Beta 2 (TPSB2) were also upregulated in the brain from depression model mice." (PMID 41556446, 2026). "Similarly, the mast cell‐specific proteases (CMA1, CPA3, and TPSB2) that were increased in depression model mice were down‐regulated by DSCG treatment as well." (PMID 41556446, 2026).
emphysema (1 paper, 2021). "For females the top differential emphysema-restricted genes are the mast cell specific genes TPSB2, TPSAB1 and CPA3." (PMID 34145303, 2021).
gastric cancer (1 paper, 2023). A primary or metastatic malignant neoplasm involving the stomach. "A growing evidence now shows that TPSB2 expression is a potential prognostic marker in cancers including gastric cancer." (PMID 37938151, 2023).
itch (1 paper, 2022). "Pruritogens, including TAC1, IL-2, IL-31, TPSAB1, TPSB2, and TPSG1, and the key enzymes that are attributed to itch, including HDC and TPH1, were detected by RNA-seq." (PMID 35632808, 2022).
Nephroblastoma (1 paper, 2014). An embryonal neoplasm characterized by the presence of epithelial, mesenchymal, and blastema components. "In contrast, levels of IL-16; IL-31; insulin receptor (IR); immunoglobulin M (IgM); Karyopherin-a2; nephroblastoma overexpressed (NovH, also known as insulin-like growth factor binding protein 9); SCF sR; TPSB2; VEGF sR2; and sL-Selectin decreased following treatment." (PMID 25100134, 2014).
non-small cell lung carcinoma (1 paper, 2021). A group of at least three distinct histological types of lung cancer, including non-small cell squamous cell carcinoma, adenocarcinoma, and large cell carcinoma. "As for the other six cell subtypes, previous studies showed that a low TPSB2 expression level is one of the typical expression patterns in cells from the brain metastasis of non-small cell lung cancer, implying the accuracy and efficacy of our predicted rules." (PMID 34575089, 2021).
Obesity (1 paper, 2020). Accumulation of substantial excess body fat. "In a different study examining a mixed cohort of persons without or with obesity, the expression of MC-tryptase (TPSB2) in VAT did not associate with parameters of glucose homeostasis or insulin sensitivity." (PMID 32575785, 2020). "Contrary to our hypothesis, patients with obesity and low VAT-MC gene expression (below median expression of both TPSB2 and CMA1) were either not significantly different, or in some parameters trended to, or exhibited significantly worse clinical parameters." (PMID 32575785, 2020). "In the independent validation, cohort 1 of n = 32 patients with obesity whose VAT gene expression was assessed by microarrays, all MC genes probe sets (KIT, TPSB2, CMA1) exhibited significant negative correlations with macrophage gene probes (CD68, Mac2, IGTAX(CD11c))." (PMID 32575785, 2020).
pericarditis (1 paper, 2018). An inflammatory process affecting the pericardium. "The pfhA region, consisting of the genes tpsB1, tpsB2, pfhA1 and pfhA2, is related to the pathogenicity of P. multocida type A. The highly pathogenic strains produce necrotic bronchopneumonia, fibrinous pleuritis and pericarditis in pigs and can be identified by PCR of the pfhA2 gene." (PMID 30134904, 2018).
prostatitis (1 paper, 2022). An infectious or non-infectious inflammatory process affecting the prostate gland. "The suppression of mast cell tryptase (TPSB2), an indicator of mast cell degranulation, also confirmed the therapeutic potential of DFO and EDA in inhibiting mast cell activation of prostatitis." (PMID 35755168, 2022).
sarcoma (1 paper, 2021). A usually aggressive malignant neoplasm of the soft tissue or bone. "In the undifferentiated sarcoma cohort, TPSB2 expression is decreased when ATRX is altered (based on RNAseq analysis) without reaching significance (p = 0.32)." (PMID 33946962, 2021).
urticaria (1 paper, 2023). A vascular reaction of the skin characterized by erythema and wheal formation due to localized increase of vascular permeability. "We found significant trans-pQTL associations of the GCSAML urticaria-associated variant with plasma levels of five proteins encoded by TPSAB1, TPSB2, KIT, SELP, and SIGLEC6 (P-values < 1.0 × 10−7)." (PMID 37430141, 2023).
viral infection (1 paper, 2022). "TPSB2 and CMA-1 have been demonstrated to induce vascular leakage in response to viral infection, which may explain the increased lung damage observed in CT scans." (PMID 36225927, 2022).
tumor (12 papers, 2018 to 2025). "Moreover, FGL1 was positively associated with the CD3D expression and negatively associated with FOXP3, S100A9, and TPSB2 within the tumor site." (PMID 36268014, 2022). "Third, tumor subsets enriched for immune markers, including cytotoxic immune genes (e.g., Prf1, Gzmb, Gzmg) and mast cell protease genes (e.g., Mcpt1, Cma1, Tpsb2)." (PMID 40171265, 2025). "The corresponding heatmap depicted the high-expression profiles of various cell types in marker genes such as KRT19, VWF, ACTA2, CD68, and TPSB2, effectively distinguishing immune, stromal, and tumor cell components." (PMID 41488617, 2025). "The cell type-specific markers we used for cell annotation were as follows: T cell (CD3D); NK cell (KLRD1 and NKG7); plasma cell (IGKC and JCHAIN); Mast cell (KIT and TPSB2); tumour cell (CA9, NDUFA4L2 and SLC17A3); endothelium (PECAM1, PTPRB and KDR); mesangial cell (ACTA2 and PDGFRB)." (PMID 40830065, 2025). "The most significant downregulated gene in IO-exposed tumor FOV was TPSB2 (FDR = 0.019)." (PMID 39639369, 2024). "In addition, a significantly high expression of the gene set of mast cell proteinase CPA3, TPSAB1, and TPSB2 was also noted in the tumor adjacent lungs (Tukey HSD test: p < 2.0 × 10−7 for each pair of comparisons)." (PMID 29483918, 2018).
cancer (8 papers, 2021 to 2025). A tumor composed of atypical neoplastic, often pleomorphic cells that invade other tissues. "TPSB2 showed similar expression in normal and cancer tissues." (PMID 40264151, 2025). "The hypergeometric distribution showed that in the cancer region, TM4SF1 + cancer cells (Epi-C0) colocalized with the two subtypes of NK cells (T/NK-C4: GNLY and T/NK-C5: NKG7) and mast cells (Mye-C0: TPSB2, Mye-C9: CPA3)." (PMID 36434043, 2022). "The cancer cell subtypes enriched in the cancer region were CRABP2 + cancer cells (Epi-C3), and NK cells (T/NK-C5: NKG7) and mast cells (Mye-C0: TPSB2, Mye-C9: CPA3) were also located in the cancer region." (PMID 36434043, 2022). "At both the mRNA level and the protein level, the levels of ZBTB7C, TPSB2, MS4A2, CD19, and MS4A1 in CRC tissues were lower than those in normal tissues adjacent to the cancer." (PMID 33946045, 2021). "In another case of MIA (TD6), the cancer cell subtypes enriched in the cancer region, including Clara-like cancer cells (Epi-C1), NK cells (T/NK-C4: GNLY and T/NK-C5: NKG7), Tregs (T/NK-C6: FOXP3) and mast cells (Mye-C0: TPSB2, Mye-C9: CPA3), were also located in the cancer region." (PMID 36434043, 2022).
TPSB2 also shares sentences with these, for which no sentence is quoted: Allergy (1 paper); atrial fibrillation (1); Hip Osteoarthritis (1); lung adenocarcinoma (1); mastocytoma (1); skin tumors (1).